C1QBP (complement C1q binding protein)
Diseases named in the same sentence as C1QBP in open-access papers (continued):
Sharing a sentence is not in itself a finding about the gene and the disease.
HCMV infection (2 papers, 2013 to 2024). "Of the cellular proteins that were confirmed to associate with IE2-p86 by immunoprecipitation, C1QBP was further shown to be upregulated by HCMV infection and colocalized with IE2-p86, UL84 and UL44 in the virus replication compartment of the nucleus." (PMID 24358118, 2013). "Taken together, these data indicated that C1QBP was upregulated by HCMV infection and C1QBP colocalized with the viral proteins IE2-p86, UL84, and UL44 in the virus replication compartments." (PMID 24358118, 2013). "In this study, we found that C1QBP not only associates with IE2-p86 at all three time-points and but also was upregulated by HCMV infection." (PMID 24358118, 2013). "We further confirmed that upon HCMV infection, there is significant accumulation of C1QBP in the nucleus besides the mitochondrion." (PMID 24358118, 2013). "Taken together, the importance of C1qBP in one or more steps of the HCMV viral lifecycle is highlighted by the fact that the reduced expression of C1qBP during HCMV infection ablates the production of essential viral proteins and significantly inhibits viral replication." (PMID 39066333, 2024). "Multiple studies have demonstrated that HCMV infection in cells results in an increased expression of C1qBP and the translocation of C1qBP from the cytoplasm to the nucleus via an unknown mechanism." (PMID 39066333, 2024). "Though the mechanism of C1QBP upregulation remains to be investigated, we speculate the transcription of C1QBP is increased by HCMV infection, like many other genes that were upregulated during the HCMV infection." (PMID 24358118, 2013). "Since HCMV infection upregulates cellular gene expression and C1QBP is associated with the IE2-p86, UL84 and UL44 in HCMV-infected cells, we hypothesized that HCMV infection may affect C1QBP expression or its localization within the cell." (PMID 24358118, 2013). "Cellular protein C1QBP interacted with the IE2-p86 early after infection and was upregulated by HCMV infection." (PMID 24358118, 2013).
laryngeal squamous cell carcinoma (2 papers, 2022 to 2024). A squamous cell carcinoma that arises from the larynx. "circMTCL1, upregulated in the advanced laryngeal squamous cell carcinoma (LSCC), could recruit C1QBP protein and inhibit its ubiquitin-proteasome-mediated degradation to exert oncogenic biological characteristics by promoting cell proliferative capability and invasive and migrative abilities." (PMID 39519039, 2024).
liver cancer (2 papers, 2018 to 2025). An epithelial or non-epithelial malignant neoplasm that arises from the liver. "However, the impact of C1QBP loss on the radiation sensitivity of liver cancer cells and the underlying mechanisms remains unclear." (PMID 40429658, 2025).
liver fibrosis (2 papers, 2021 to 2024). "Similarly, exosomal CD44v6/complement C1q binding protein (C1QBP) also activates hepatic satellite cell for liver metastasis and liver fibrosis in mice." (PMID 34671031, 2021).
lung adenocarcinoma (2 papers, 2019 to 2025). A carcinoma that arises from the lung and is characterized by the presence of malignant glandular epithelial cells. "Analyzing 566 The Cancer Genome Atlas samples alongside lung adenocarcinoma (LUAD)-specific microarray and single-cell sequencing data, we identified 109 cuproptosis-associated genes, of which C1QBP and PFKP emerged as key prognostic markers." (PMID 41041346, 2025). "Upregulation of C1QBP (1.468-fold) was observed in lung adenocarcinoma (LUAD) of the Landi dataset and a 1.838-fold increase was observed in lung squamous cell carcinoma (LUSC) of Wachi dataset (as representative data)." (PMID 30991713, 2019).
metastasis (2 papers, 2023 to 2025). The spread or migration of cancer cells from one part of the body (where they first appeared) to another. "In addition, simultaneous high expression of exosomal CD44v6 and C1QBP correlated with a worse prognosis and a higher risk for postoperative PDAC liver metastasis." (PMID 40182121, 2025). "A clinical study has shown that EV CD44v6 and C1QBP expression was higher in patients with PDAC and liver metastasis than in those without liver metastasis." (PMID 40182121, 2025).
pancreatic ductal adenocarcinoma (2 papers, 2021 to 2022). An infiltrating adenocarcinoma that arises from the epithelial cells of the pancreas. "Exosomal CD44v6/C1QBP from pancreatic ductal adenocarcinoma cells contributes to premetastatic niche formation in the liver and may be used for the diagnosis of pancreatic ductal adenocarcinoma liver metastasis." (PMID 35388172, 2022).
preeclampsia (2 papers, 2025). Preeclampsia is a hypertensive disorder of pregnancy that is characterized by new-onset hypertension with proteinuria presenting after 20 weeks of gestation, and depending on mild or severe forms may initially present with severe headache, visual disturbances, and hyperreflexia. "The high levels of expression of RPAIN in preeclampsia may affect the biological function such as proliferation, apoptosis, and invasion of placental trophoblast cells through C1QBP, which participates in the occurrence and development of preeclampsia." (PMID 40454173, 2025). "As shown in the disordered expression of C1QBP and CYP19A1 in PE tissues, the dysregulation of this novel signaling pathway may potentially contribute to the pathogenesis of preeclampsia by interfering with the normal induction of trophoblast differentiation." (PMID 40589522, 2025).
sarcoma (2 papers, 2022 to 2023). A usually aggressive malignant neoplasm of the soft tissue or bone. "The correlation between C1QBP and C1S was negative in TCGA-SARC, and their respective prognostic values in sarcoma were inverse." (PMID 35493104, 2022).
actinic keratosis (1 paper, 2021). A precancerous lesion of the skin composed of atypical keratinocytes. "Moreover, p32/C1qbp transcription patterns are associated with the outcomes of influenza A, actinic keratosis, and cancers." (PMID 34421919, 2021).
anemia (1 paper, 2020). A reduction in the number of red blood cells, the amount of hemoglobin, and/or the volume of packed red blood cells. "Hematopoietic cell-specific genetic deletion of p32/C1qbp (p32cKO) in mice caused anemia and B-lymphopenia without reduction of hematopoietic stem/progenitor cells." (PMID 33103089, 2020).
autoimmune disease (1 paper, 2021). A disorder resulting from loss of function or tissue destruction of an organ or multiple organs, arising from humoral or cellular immune responses of the individual to their own tissue constituents. "Considering the varied expression of p32/C1qpb in many cell types and organs, we promote further study on the association between p32/C1qbp and mtROS focusing on the pathogenesis of autoimmune diseases in mice and humans." (PMID 34421919, 2021). "In particular, because p32/C1qbp and mtROS may have important roles in autoimmune diseases, further analyses are essential." (PMID 34421919, 2021).
brain cancer (1 paper, 2022). A primary or metastatic malignant neoplasm affecting the brain. "Myc can upregulate C1qbp transcription, resulting in the regulation of glutamine metabolism, which suggest that a high level of Myc in malignant brain cancers is accompanied by increased expression of C1QBP." (PMID 36467687, 2022).
brain tumors (1 paper, 2015). "Here we report that p32/C1QBP is upregulated by Myc in malignant brain tumors." (PMID 25528767, 2015).
breast invasive carcinoma (1 paper, 2019). "Expression of C1QBP gene was also significantly (p < 1.00E−12) higher in breast invasive carcinoma (BRIC) than the normal counterpart in TCGA database." (PMID 30991713, 2019). "Upregulation of C1QBP was found to be the most frequent alteration type in metaplastic breast cancer (MBC), breast invasive carcinoma (BRIC), breast invasive ductal carcinoma (BRIDC), and breast invasive lobular carcinoma (BRILC)." (PMID 30991713, 2019).
cholangiocarcinoma (1 paper, 2024). A carcinoma that arises from the intrahepatic biliary tree (intrahepatic cholangiocarcinoma) or from the junction, or adjacent to the junction, of the right and left hepatic ducts (hilar cholangiocarcinoma). "They found significantly higher C1QBP mRNA and protein expression in the cholangiocarcinoma cell lines compared to the normal cell lines." (PMID 39284282, 2024).
cleft lip (1 paper, 2025). Congenital defect in the upper lip where the maxillary prominence fails to merge with the merged medial nasal prominences. "For example, TBX22 is associated with facial developmental defects such as a cleft lip and a cleft palate in humans, whereas C1QBP plays an essential role in regulating mitochondrial morphology, metabolism, and autophagy." (PMID 40565519, 2025).
colon adenocarcinoma (1 paper, 2019). "Analysis of the Notterman dataset revealed a significantly higher expression of C1QBP in colon adenocarcinoma (COAD) patients compared to their normal counterparts." (PMID 30991713, 2019).
colorectal adenocarcinoma (1 paper, 2019). The most common type of colorectal carcinoma. "Alterations in the C1QBP gene (TCGA PanCanAtlas dataset) were found in COAD, mucinous adenocarcinoma of the colon and rectum (MACR), rectal adenocarcinoma (RAD), and colorectal adenocarcinoma (CA)." (PMID 30991713, 2019).
dermatitis (1 paper, 2021). An inflammatory process affecting the skin. "Because the IL-23/IL-17 axis is an important pathway in psoriasis pathogenesis, we examined whether the loss of p32/C1qbp in hematopoietic cells inhibit the IL-23/IL-17-mediated pathogenesis of psoriasis-like dermatitis." (PMID 34421919, 2021).
diabetes (1 paper, 2021). "The results showed that possessing the G allele in either rs3786054 or rs8070740 loci in C1QBP and RPAIN genes, respectively, increased the risk of H1N1 infection up to 3.3 folds, regardless of the patient’s age, BMI, diabetes, and hypercholesterolemia." (PMID 33766078, 2021).
diffuse large B-cell lymphoma (1 paper, 2019). "In the Oncomine database, expression of C1QBP was enhanced approximately 3-fold in diffuse large B-cell lymphoma (DLBC)." (PMID 30991713, 2019).
glaucoma (1 paper, 2020). Increased pressure in the eyeball due to obstruction of the outflow of aqueous humor. "Bioinformatic analysis of POAG‐related autoantigens showed a strong association with the PDGFRB pathway and also increased levels of PNMA2, TARS, and C1QBP autoantibodies in the serum of POAG patients as potential glaucoma biomarkers." (PMID 32140226, 2020). "Lastly, we could confirm the presence of increased levels of AAbs against PNMA2, TARS and C1QBP in the serum of POAG patients that deserve to be further analysed as potential glaucoma biomarkers." (PMID 32140226, 2020). "While antibodies to HSPD1 (mitochondrial 60 kDa heat shock protein) have frequently been observed in association with glaucoma, AAbs to C1QBP, TARS and PNMA2 have not yet been described in the disease context." (PMID 32140226, 2020). "Therefore, we wanted to evaluate whether validated glaucoma‐related AAbs to PNMA2, TARS, C1QBP and HSPD1 hold the potential to serve as biomarker candidates." (PMID 32140226, 2020).
glucose metabolism disorder (1 paper, 2021). "Depletion of C1QBP inhibited cell proliferation and metastasis of TNBC cells, suggesting that the decreased tumorigenicity of TNBC cells might be caused by mitochondrial dysfunction and glucose metabolism disorder." (PMID 33708767, 2021).
heart failure (1 paper, 2024). Inability of the heart to pump blood at an adequate rate to meet tissue metabolic requirements. "The NDUFA6 p.Ile94LysfsTer44 variant has been reported in a patient with recurrent exertional rhabdomyolysis, and the C1QBP p.Thr40AsnfsTer45 and PPA2 p.Glu172Lys variants have been reported in autosomal recessive mitochondrial cardiomyopathies with heart failure and sudden cardiac death." (PMID 39457051, 2024).
lactic acidosis (1 paper, 2017). Metabolic acidosis characterized by the accumulation of lactate in the body. "Typical of mitochondrial disorders, the C1QBP defect resulted in a spectrum of manifestations that ranged from infantile lactic acidosis (probands S1 and S2) to childhood myopathy (proband S3) to late-onset myopathy with PEO (proband S4)." (PMID 28942965, 2017). "C1QBP defects manifested with a spectrum of symptoms ranging from infantile lactic acidosis (in probands S1 and S2) to childhood myopathy, PEO, and later peripheral neuropathy (in proband S3) to adult-onset myopathy with PEO (in proband S4)." (PMID 28942965, 2017).
liver disease (1 paper, 2024). "For instance, some of the complement proteins identified in this study, including C1QBP, C4BPA, CLU, and SERPING1, have also been identified in proteomic analyses as potential biomarkers in metabolic dysfunction-associated steatotic liver disease/metabolic dysfunction-associated steatohepatitis." (PMID 38573776, 2024).
lymphoma (1 paper, 2019). A malignant (clonal) proliferation of B- lymphocytes or T- lymphocytes which involves the lymph nodes, bone marrow and/or extranodal sites. "Overall, these data suggest the altered expression of C1QBP and its association of risk in lymphoma." (PMID 30991713, 2019). "Lymphoma patients’ group with a high expression level of C1QBP mRNA showed significantly poor overall survival compared to the low expression group." (PMID 30991713, 2019). "C1QBP expression was greatly upregulated in lymphoma compared to the normal counterparts; thus, we elaborately analyzed the expression of C1QBP and its relevance in clinical outcomes in lymphoma datasets." (PMID 30991713, 2019). "Next, we focused on the clinical outcomes of lymphoma patients with C1QBP expression." (PMID 30991713, 2019).
mental disorder (1 paper, 2025). A disease that has its basis in the disruption of mental process. "Here, both C1qbp and Hspd1 fit this profile, which raises the possibility that these proteins are a link between the immune system and this mental disorder." (PMID 40299488, 2025).
muscle atrophy (1 paper, 2024). The loss of muscle tissue due to inactivity or disease. "Therefore, anti-C1qbp treatment modalities, such as anti-C1qbp blocking antibodies and C1qbp inhibitors, may be developed to overcome diseases associated with muscle atrophy." (PMID 38977785, 2024).
oral squamous cell carcinoma (1 paper, 2025). "The correlation between proteasome activator 28γ (PA28γ) and C1QBP in the carcinogenesis and development of oral squamous cell carcinoma (OSCC)." (PMID 40736231, 2025). "(D) Western blot analysis of C1QBP in four oral squamous cell carcinoma (OSCC) cell lines with PA28γ overexpression." (PMID 40736231, 2025). "Here, using oral squamous cell carcinoma (OSCC) as the main research model, and combining co-immunoprecipitation (Co-IP), proximity ligation assays (PLA), AlphaFold 3-based molecular docking, and truncation constructs, we discovered that PA28γ interacted with complement 1q binding protein (C1QBP)." (PMID 40736231, 2025).
progressive external ophthalmoplegia (1 paper, 2020). A mitochondrial myopathy characterized by slowly progressive paralysis of the levator palpebrae, orbicularis oculi, and extraocular muscles. "Dysfunction of p32/C1qbp impairs fetal development and immune responses, and its genetic mutations are related to human diseases such as cardiomyopathy and progressive external ophthalmoplegia." (PMID 33103089, 2020).
prostate tumors (1 paper, 2019). "DNAAF2, U2AF1, C1QBP, Snapin, or HDLBP are upregulated in prostate tumors or PCa cell lines." (PMID 31694235, 2019).
psoriasis (1 paper, 2021). An autoimmune condition characterized by red, well-delineated plaques with silvery scales that are usually on the extensor surfaces and scalp. "Because we thought that p32/C1qbp-dependent DC activation was associated with the exacerbation of psoriasis, we analyzed the relationship between p32/C1qbp and DC activation following IMQ stimulation in vitro." (PMID 34421919, 2021). "Our findings suggest that p32/C1qbp, which functions as a multifunctional chaperone protein in mitochondria, is an important genetic factor involved in psoriasis." (PMID 34421919, 2021). "In this study, we have demonstrated that p32/C1qbp is an important factor for the exacerbation of psoriasis through mtROS." (PMID 34421919, 2021). "We found that the gene expression of p32/C1qbp was significantly increased in lesional skin from patients with psoriasis, compared with healthy controls." (PMID 34421919, 2021). "We hypothesized that p32/C1qbp is involved in immune cell-mediated exacerbation of psoriasis (e.g., via DCs and T cells)." (PMID 34421919, 2021). "The gene expression of p32/C1qbp was increased during IMQ-induced psoriatic inflammation, similar to human psoriasis." (PMID 34421919, 2021). "Although our study does not fully show the mechanism underlying the exacerbation of psoriasis through IMQ-induced DC activation, we have elucidated a portion of the mechanism underlying exacerbation of psoriasis by p32/C1qbp and mtROS-dependent pathways." (PMID 34421919, 2021).
sarcopenia (1 paper, 2024). Progressive decline in muscle mass due to aging which results in decreased functional capacity of muscles. "This study demonstrated that extracellular C1qbp is a novel therapeutic target for sarcopenia that meets these conditions." (PMID 38977785, 2024). "Further studies are needed to determine what the concentration of C1qbp in the blood is and whether sarcopenia correlates with the level." (PMID 38977785, 2024).
small cell lung carcinoma (1 paper, 2025). Small cell lung cancer (SCLC) is a highly aggressive malignant neoplasm, accounting for 10-15% of lung cancer cases, characterized byrapid growth, and early metastasis. "In contrast, apCAFs exert tumor-suppressive effects by producing C1q in small cell lung cancer, which binds to the C1qbp on the surface of CD4+ effector T cells, preventing their apoptosis." (PMID 39891284, 2025).
testis cancers (1 paper, 2019). "In databases using U133 platform, C1QBP expression is upregulated in certain cancer types including bladder, breast, colon, lung, prostate, stomach, and testis cancers." (PMID 30991713, 2019).
type 2 diabetes (1 paper, 2015). "We selected 14 disallowed genes for analysis based on their identification in 2 independent studies (C1qbp, Cd302, Cxcl12, Igfbp4, Ldha, Lmo4, Maf, Oat, Pdgfra, Slc16a1, and Smad3) and/or other criteria including up-regulation in type 2 diabetes (Acot7, Ldha, and Pdgfra)." (PMID 26038943, 2015).